CD4 (CD4 molecule)
Diseases named in the same sentence as CD4 in open-access papers (continued):
Sharing a sentence is not in itself a finding about the gene and the disease.
pancreatic cancer (continued). "We demonstrate that SRF617 enhances CD4+ T-cell proliferation in the presence of ATP and induces higher numbers of CD8+ T cells in the TME of an orthotopic pancreatic tumor in vivo." (PMID 37219538, 2023). "In anticancer immunity, the complex interaction between immune cells such as NK, CD4+ T, and CD8+ T cells can significantly affect the survival rate, which has been reported in tumor‐infiltrating lymphocytes in pancreatic cancer." (PMID 37792639, 2023). "A clinical trial (NCT01547260) found lenalidomide augmented a significant increase in the numbers of CD4+ and CD8+ T cells in patients with advanced pancreatic cancer." (PMID 37064113, 2023). "We examined the expression of ITGA2, MET, E-cadherin, PD-L1, CD4, and CD8 proteins in 62 pancreatic cancer tissue samples using multi-tissue immunofluorescence and immunohistochemistry techniques." (PMID 37881431, 2023). "Its high expression has been found to impact the MET status and the expression of PD-L1, CD4, and CD8 in the immune microenvironment of pancreatic cancer patients, leading to a poor prognosis." (PMID 37881431, 2023). "Cytokines secreted by cancer cells and other stromal cells in pancreatic tumor microenvironment, such as TGF-β1 induce the differentiation of CD4+ CD25- T cells into CD4+ CD25+ Foxp3+ Treg cells." (PMID 37064113, 2023). "Mouse pancreatic tumor responded to R848 with CD8+ T cells increasing and CD4+CD25+FOXP3+ regulatory T cells decreasing." (PMID 37063284, 2023). "To identify the specific mechanism, we first cocultured CD4+CD25− T cells with WT, CD73-overexpressing (OE), and CD73 KO pancreatic cancer cells, and cells treated with TGF-β were used as the positive control." (PMID 37291128, 2023). "One mouse experiment of pancreatic cancer confirmed that the combination PD-1 inhibitors and OX40 agonists reduced the proportion of Treg and exhausted T cells, and increased the number of CD4+ and CD8+ T cells in pancreatic tumors." (PMID 36766879, 2023). "Inhibition of PAK1 also stimulated the intra-tumoral CD4+ and CD8+ T cells and suppressed pancreatic cancer." (PMID 36672500, 2023). "A recent study demonstrated that Klf5 loss led to a reduced number of myeloid-derived cells, particularly granulocytic myeloid-derived suppressor cells (gMDSCs), but an augmented number of both CD4+ and CD8+ T cells in pancreatic cancer models." (PMID 36923542, 2023). "Our study discovered that the expression of CD4+ and CD8+ T cells in pancreatic cancer tissues was significantly reduced, while the expression of ITGA2 was increased." (PMID 37881431, 2023). "Histopathological and immunohistochemical analyses showed that the recombinant virus rPRV-IL-18-γ increased the infiltration ratio of CD4+T cells, CD8+T cells and inflammatory cells in the tumors of pancreatic cancer mice." (PMID 37513021, 2023). "Previous studies have revealed that peripheral CD4+FOXP3+ Tregs and MDSCs decreased after gemcitabine-based chemotherapy in patients with pancreatic cancer." (PMID 36333670, 2022). "Decreased circulating CD4+ and CD8+ T cell populations are observed in patients with pancreatic cancer when compared with healthy individuals." (PMID 35935871, 2022). "CLEC7A encodes dectin, which helps to form the TME and which can suppress CD4+ and CD8+ T cells in pancreatic cancer." (PMID 35783358, 2022). "Early after infusion of human PBMCs, iPDX mice demonstrated engraftment of human CD4+ and CD8+ T cells in the blood of both colorectal and pancreatic cancer patient-derived models that persisted for up to 8 weeks." (PMID 36095023, 2022). "In contrast, CD4 T cells, γδT cells, MAIT cells, NK cells, Tfh cells, and CD8T cells were downregulated immune cells in pancreatic cancer." (PMID 36358856, 2022). "It was recently shown that the number of both tumor- and stroma-infiltrating CD4+ and CD8+ T cells were reduced in pancreatic tumors with high tumor budding." (PMID 34203869, 2021).
pancreatic cancer (continued). "After co-culture with pancreatic cancer cells overexpressing DKK3, the glucose uptake markedly, proliferation enhanced and apoptosis inhibited in CD4+ T cells." (PMID 34391478, 2021). "Although both CD4+ and CD8+ T cells are present in pancreatic cancer, they are frequently located away from the tumour cell nests." (PMID 34784792, 2021). "In this study, our results show that the L-4F treatment increased the infiltration of CD3+CD4+ T and CD3+CD8+ T cells into the mouse spleen and pancreatic cancer tissue to various degrees." (PMID 32425796, 2020). "Compared with control group, significant higher frequencies of memory CD4+ T cells (CD4+ CD44+ CD62L−) and CD8+ T cells (CD8+ CD44+ CD62L−) in tumor and tumor‐draining LN regions were observed in the subcutaneous pancreatic tumors." (PMID 32508058, 2020). "The analysis demonstrated increased levels of cells double positive for CD4/GL13 and CD8/GL13 in the pancreatic cancer microenvironment that reached a statistical significance in the TC versus NAT (p-value < 0.05)." (PMID 32645996, 2020). "There is compelling evidence that CD4+ CD25+ Foxp3+ regulatory T cells (Tregs) contribute to maintain immune tolerance in the TME particularly in pancreatic cancer." (PMID 33013885, 2020). "Thus, consistent with previous data in the genetically engineered mouse model of pancreatic cancer (KPC mice), we have found that PDAC is characterized by a strong accumulation of immunosuppressive cell populations (MDSCs, Treg cells) associated with low levels of activated CD4+ and CD8+ T cells." (PMID 32038621, 2019). "Recent work by the Rosenberg group revealed KRASmut-specific CD4+ T-cells, and KRAS-specific tumor-infiltrating IgG B-cells were identified in patients with pancreatic cancer." (PMID 31665076, 2019). "Mechanistically, dectin-1 binds to galectin-9, resulting in immunogenic or tolerogenic phenotypes of CD4 + and CD8 + T cells that promote tumour progression in pancreatic cancer." (PMID 31832021, 2019). "The percentages of MDSCs and TAMs are elevated significantly with the progression of pancreatic cancer; conversely, the percentages of CD8+ and CD4+ T cells are significantly reduced." (PMID 30987642, 2019). "Here, we demonstrate that primary murine CD4+ T cells, expressing PD1-CD28 fusion protein, overcome PD-L1-induced T cell anergy in murine models of pancreatic cancer and non-Hodgkin lymphoma." (PMID 30214445, 2018). "In pancreatic cancer, variable frequencies of endogenous CD8+ T cells, CD4+Foxp3− T cells, and CD4+Foxp3+ regulatory T cells (Treg) were reported." (PMID 30104497, 2018). "API has been demonstrated to modulate immune response by inhibiting regulatory T cells (Tregs) and increasing CD4+ and CD8+ T cells at the tumor site in pancreatic cancer." (PMID 28674496, 2017). "We and others have reported that tumor-infiltrating CD4+, CD8+, or CD45RO+ T cells have a significant prognostic value in several human cancers, including pancreatic cancer." (PMID 25888293, 2015). "Increased percentages of CD4+CD25+ Tregs in PBMCs have been reported in patients with several types of human cancer, including pancreatic cancer." (PMID 24637664, 2014). "In that study, we also used flow cytometry to confirm that the FOXP3+ cells were also CD3+CD4+CD25+CD127−, thus strengthening the suggestion that FOXP3 can serve as a useful marker for Treg in pancreatic cancer." (PMID 25191901, 2014). "ONTAK has also been shown to decrease the number of circulating CD4+CD25+ Treg cells and the suppression mediated by these cells in patients with ovarian, lung, breast, and pancreatic cancer." (PMID 23378947, 2013). "In patients with posterior uveal melanoma, pancreatic carcinoma, osteosarcoma, HCC, and RCC that were treated with HIFU, increased percentages of CD4+ T cells and a higher CD4+/CD8+ ratio were observed." (PMID 22242035, 2011).
pancreatic cancer (continued). "Further immunohistochemical analyses on the distribution of CD4+ and CD8+ T cells revealed the infiltration of CD4+ and CD8+ T cells into areas of B7-H3 positive pancreatic cancer cells." (PMID 20035626, 2009). "The amount of apCAF (CD74+, PDGFα+) in pancreatic cancer was positively correlated with MSLN expression (P = 0.0026), but were negatively correlated with the amount of effector immune cells such as CD8+ T cells (p = 0.0165) and IFN‐γ+CD4+ T cells (p = 0.0014)." (PMID 39887656, 2025). "The inclusion of cfDNA signals at CD4+ T cell specific open chromatin regions did not improve prediction accuracy in the pancreatic cancer dataset." (PMID 41225146, 2025). "T cells CD8, T cells CD4 memory activated, regulatory T cells (Tregs), monocytes, M0 macrophages, macrophages M2 emerged as the primary immune cell populations influenced by PLA2G16 expression in pancreatic cancer." (PMID 40458552, 2025). "The negative correlations between apCAFs and CD8+ T cells/IFN‐γ+CD4+ T cells are further confirmed in human pancreatic cancer tissues." (PMID 39887656, 2025). "When CD4+ T cell ATAC-seq peaks were used as the reference, a larger set of differentially enriched loci was detected, showing a consistent trend toward increased cfDNA signals in pancreatic cancer samples." (PMID 41225146, 2025). "Additionally, we observed comparable chemotaxis of CD4+ T cells and CD8+ T cells by PANC-1 pancreatic cancer cells after photon, proton, or carbon ion irradiation with biological and physical equivalent doses." (PMID 40811032, 2025). "Pancreatic tumor samples from mice treated with either engineered DCs, LVV control DCs, or untreated controls were collected, and paraffin-embedded sections were stained using anti-CD4 and CD8 antibodies." (PMID 40733726, 2025). "Pancreatic cancer cells escape immunity by secreting cytokines such as IL-10 and TGF-β, immunosuppression as a result of these cytokines affects the immune function by inhibiting the infiltration of CD4+ and CD8+ T cells in the cancer cells." (PMID 38973003, 2024). "In addition, WDR5 ablation effectively results in the downregulation of immune checkpoints (PD-1, PD-L1, and Spp1) and immunosuppressive cytokines (TGFβ and IL6) in pancreatic tumor microenvironments, leading to improved CD8+/CD4+ T-cell infiltration." (PMID 39201460, 2024). "To test this, we depleted T cells using anti-CD4 and anti-CD8 antibodies (200 mg/mouse) in 4.5 weeks old PKT mice treated with vehicle or Uro A, and pancreatic tumors were harvested for endpoint analysis (after 3 weeks), or the treatment was continued until mice were moribund." (PMID 37448553, 2023). "To investigate whether ITGA2 regulates immune function in pancreatic cancer, we conducted ITGA2, CD4, and CD8 assays on postoperative specimens from 62 patients with pancreatic cancer." (PMID 37881431, 2023). "Results from the univariate analysis revealed that the expression of ITGA2+ cells was significantly associated with overall survival time, as well as the expression of CD4+ and CD8+T cells, degree of tissue differentiation, TNM stage, lymphatic metastasis, and local invasion in pancreatic cancer." (PMID 37881431, 2023). "We generated a novel panel of pancreatic cancer cell lines with stable expression of a model antigen and observe that CD103+ CD8 T cell formation is dependent on antigen-specific interactions in the lymph node but occurs independently of CD4 T cell help." (PMID 37072485, 2023). "The boxplot demonstrated varying degrees of infiltration for several immune cell types between pancreatic cancer tissues and normal tissues, such as B cells naive, B cells memory, T cells CD8, T cells CD4 naive, NK cells resting, NK cells activated, Monocytes, among others." (PMID 37753069, 2023).
pancreatic cancer (continued). "This work sets the stage for future development of optimized CD4+-specific and CD8+-specific T cell responses in a personalized vaccine approach that will be essential for successful therapeutic outcomes in hard-to-treat cancer types such as pancreatic cancer." (PMID 38063199, 2023). "Next, we cocultured CD4+ CD25+ Tregs with WT, CD73 OE, or CD73 KO pancreatic cancer cells." (PMID 37291128, 2023). "Furthermore, CIBERSORTx was used to evaluate 22 immune cell relative proportions, high numbers of neutrophils and macrophage M2, combined with low numbers of activated CD4+ memory T cells and CD8+ T cells were infiltrating in pancreatic cancer patients." (PMID 35150061, 2022). "Furthermore, blockage of CTLA-4/CD80 interaction is sufficient to induce CD4+ T cell infiltration into pancreatic tumours, demonstrating that the CTLA-4/CD80 axis regulates T cell infiltration in pancreatic cancer." (PMID 35892707, 2022). "In contrast to the absence of cytotoxic T cells in the pancreatic tumors, CD4+ T cells were relatively abundant and showed expression of activation markers." (PMID 35793870, 2022). "Similarly, in pancreatic cancer cases [pancreatic adenocarcinoma (PAAD); n = 179], FAT1 expression correlated inversely with infiltration of monocytes, CD8+ T cells, CD4+ T cells, and dendritic cells, while it correlated positively with that of MDSCs." (PMID 35720420, 2022). "In addition, we performed western blotting of DIAPHs in several pancreatic cancer cell lines and immunohistochemical staining of DIAPH1, DIAPH2, DIAPH3, CD3, CD4, and CD68 in human pancreatic tumor tissues for experimental validation." (PMID 36589226, 2022). "Moreover, activated PSCs-secreted galectin-1 promotes the apoptosis of CD3+CD4+ and CD3+CD8+ effector T cells, developing a PSC-dependent immunoprivilege in the pancreatic cancer microenvironment." (PMID 35719926, 2022). "Furthermore, our study found that co-culture with DKK3-overexpressing pancreatic cancer cells upregulated IFN-γ, IL-2, and IL-17, inhibited tIL-4 and IL-10 in activated CD4+ T cells." (PMID 34391478, 2021). "In addition, in human pancreatic cancer and mouse pancreatic tumor models (Pan02), the CCL5 level on tumor cells is elevated, while CD4+Foxp3– effector T cells preferentially express C‐C chemokine receptor 5 (CCR5)." (PMID 34977871, 2021). "Besides, our study also revealed that co-culturing with DKK3-overexpressing pancreatic cancer cells promotes the expression of CD69, CD3, CD25, CD71, and HLA-DR mRNA in CD4+ T cells." (PMID 34391478, 2021). "In this study, we found that unlike CD8+ T and CD4+ T cells, pancreatic tumor cells are selectively resistant to NK cell-mediated immune surveillance." (PMID 31024520, 2019). "It has been suggested that the co-expression of CD4+ and CD8+ cells could serve as a prognostic factor in pancreatic cancer." (PMID 30843106, 2019). "Consistent with data from intra-tumoral injected pancreas tumors, intraperitoneal administration of DMXAA triggered a significant infiltration and accumulation of CD8+ T cells within PDA tumors, with a concomitant reduction in the CD4:CD8 T cell ratio." (PMID 31036082, 2019). "Following CAR transduction, both CD26int and CD26high T cells significantly slowed the progression of pancreatic tumors, whereas bulk CD4+ and CD26neg T cells yielded little-to-no antitumor response." (PMID 29213079, 2017). "Therefore, an imbalance in effector CD4+ and CD8+ T cells and regulatory T cells is a significant impediment to treating pancreatic cancer." (PMID 25629611, 2015). "The results have confirmed that CD4+ and CD8+ T cell responses could be expanded in pancreatic cancer patients, and that these patients had an increased frequency of IFN-γ secreting CD4+ T cells, compared to the controls." (PMID 24520352, 2014).
pancreatic cancer (continued). "In this model, CD4+ T cells were critical for rejection of MUC1-positive tumours, whereas other studies suggest that CD8+ T cells are required for MUC1-specific immunity against MUC1-positive pancreatic carcinoma." (PMID 12966437, 2003). "T-cell infiltrations in the pancreatic tumors treated with LIFE Biomaterial_anti-CD40 alone or combined with CONV_5 Gy, CONV_10 Gy, CONV_20 Gy, or Flash_5 Gy alone, respectively, have shown higher permeations of CD11b or CD3, CD4, and CD8 T-cells in the tumor microenvironment." (PMID 41155910, 2025). "OX40 agonists have been explored in mouse orthotopic pancreatic cancer models, along with the administration of anti-PD1 therapy, and they have led to a reduction in regulatory and exhausted T cells and the stimulation of memory CD4+ and CD8+ T cells and B cells, resulting in tumor eradication." (PMID 40723238, 2025). "RNA-sequencing (RNA-seq) of pancreatic tumor lysates and principal component analysis revealed that KC;iASPPΔ8/Δ8 pancreata bear closer resemblance to KC than KPC pancreata and express greater Cd3, Cd4, Itgae, Pdcd1, Il10, Ccl5, Osm, and Cd274, reflective of an immunosuppressive stromal reaction." (PMID 36746936, 2023). "When we studied whether the presence of pancreatic tumours could modify the immune cell content of the pancreatic draining lymph nodes (LNs), we did not observe major modifications regarding the percentages of CD45+CD8+ cells and CD45+CD4+ cells." (PMID 36077801, 2022). "In contrast, significantly high percentages of CD4+CD3+ (42.76 ± 11.26%) and CD8+CD3+ (39.30 ± 1.10%) T cells were found in TILs, as compared to those in PBMCs CD4+CD3+ (31.64 ± 12.43%) and CD8+CD3+ (18.85 ± 9.81%), indicating active localization of T cells to pancreatic tumors." (PMID 31024520, 2019). "To determine whether the expression of B7-H3 by pancreatic cancer cells influences the distribution of tumor-infiltrating CD4+ or CD8+ T cells, we performed immunohistochemical stainings for B7-H3, CD4, and CD8 of 20 randomly chosen pancreatic cancer tissue sections." (PMID 20035626, 2009). "However, the low numbers of circulating CD4+CD25high as well as CD8+CD25high in patients before treatment was a surprising finding and in contrast to earlier reports, showing an increased proportion of CD4+/CD25+ cells in breast and pancreatic cancer patients." (PMID 17551492, 2007). "Likewise, tumour-infiltrating CD4+T-cells proliferated against its own tumour cell target, while such T-cells did not respond to heterologous, mucin-expressing pancreatic tumour cells." (PMID 10682684, 2000). "However, we observed that the frequencies of naïve T cells (including CD4 + and CD8 +) in cancer donors were much lower than that of healthy individuals, and the frequencies of Tregs were substantially higher in most cancer donors, especially in pancreatic cancer donors." (PMID 37024957, 2023). "Further experimental verification is needed to confirm the immunosuppressive role of ITGA2 in the immune regulation of pancreatic cancer microenvironment, as there is a negative correlation between ITGA2 and CD4 and CD8." (PMID 37881431, 2023). "CD4+ T cell phenotypes contained in PDAC tissues included PD-1+CD4+ T cells, of which the relative frequency was significantly increased in pancreatic tumors as compared with the non-malignant tissues (p<0.01 by Mann-Whitney test)." (PMID 35793870, 2022). "CD40 stimulation to regulatory B cells is derived from cognate CD4+ T cells in EAE, but it is not known in pancreatic cancer where antigen-specific T cell responses are not as prevalent." (PMID 35046933, 2021). "Moreover, a significantly higher frequency of T-cells (CD4+, CD8+) and NK-cells producing perforin and granzyme B compared with healthy controls were noted, which might be related to the presence of tumor antigen-specific T cells as reported in pancreatic cancer patients." (PMID 28099502, 2017).